ORMDL3 (ORMDL sphingolipid biosynthesis regulator 3)
Diseases named in the same sentence as ORMDL3 in open-access papers (continued):
Sharing a sentence is not in itself a finding about the gene and the disease.
eosinophilia (2 papers, 2017 to 2022). "There was also a small but significant increase in airway eosinophilia in the epithelial ORMDL3-expressing KOHar mice compared with WT mice (Fig E2, B)." (PMID 27623174, 2017). "ORMDL3 expression did not influence the number of TH2 cells or type 2 innate lymphoid cells recruited to the lung in response to Alternaria; however, eosinophilia was reduced in mice lacking ORMDL3." (PMID 27623174, 2017).
viral infection (2 papers, 2021 to 2025). "In our study, we found that the transcription of IFNB1 was significantly impaired in ORMDL3-overexpressing cells in response to viral infection." (PMID 40126553, 2025). "Nevertheless, the observations presented here have significant clinical implications, and warrant further investigation focusing on the precise mechanisms through which ORMDL3 moderates the inflammatory response to viral infection." (PMID 34001091, 2021). "This negative regulatory loop of antiviral innate immunity mediated by ORMDL3 may provide insights for the development of therapeutics against viral infections and tumors." (PMID 40126553, 2025). "ORMDL3 may work in multiple signaling pathways to regulating viral infection through ER stress, sphingolipid metabolism, glycolysis and other mechanisms." (PMID 34001091, 2021). "In order to determine whether ORMDL3 knockdown in epithelial cells also influences the inflammatory response to live viral infection, we silenced ORMDL3 in A549 and BEAS-2B epithelial cells and infected these cells with HRV16, one of the most common rhinoviruses." (PMID 34001091, 2021). "Thus, the results suggest a key role for ORMDL3 in the host response to viral infection." (PMID 34001091, 2021).
adult onset asthma (1 paper, 2011). "In this study, we aimed to evaluate the association of polymorphisms in ORMDL3, GSDMB, ZPBP2 and IKZF3 and adult-onset asthma in a Chinese Han population." (PMID 21985515, 2011).
bronchiolitis (1 paper, 2024). Inflammation of the bronchioles characterized by swelling of the bronchioles and mucus accumulation. "We showed that regulatory variants in the GSDMB locus may influence GSDMB and ORMDL3 expression in distinct immune cell types and that the genotype-dependent gene expression could mediate susceptibility to severe bronchiolitis." (PMID 39299705, 2024).
bronchitis (1 paper, 2017). An acute or chronic inflammatory process affecting the bronchi. "Significant differences in the prevalence and risk of bronchitis were found in genotypes of LT-α and TNF-α, but not in ALOX5, LTC4S, TBXA2R, ADAM33, NOS1 and ORMDL3 in the Inuit populations residing both in Greenland and in Denmark." (PMID 28740106, 2017).
chronic obstructive pulmonary disease (1 paper, 2020). A chronic and progressive lung disorder characterized by the loss of elasticity of the bronchial tree and the air sacs, destruction of the air sacs wall, thickening of the bronchial wall, and mucous accumulation in the bronchial tree. "Thus, polymorphisms in the A Disintegrin and Metalloprotease 33-ADAM 33 (20p13) and OrmDL3 (17q21) genes increase susceptibility to wheezing in infancy and possibly later-life Chronic Obstructive Pulmonary Disease—COPD, but not necessarily asthma." (PMID 32423152, 2020).
colon adenocarcinoma (1 paper, 2025). "We observed higher expression of ORMDL3 in lung adenocarcinoma (LUAD), colon adenocarcinoma, and lung squamous cell carcinoma compared to their corresponding normal samples." (PMID 40126553, 2025).
colon cancer (1 paper, 2023). "Accordingly, both technologies reported the overexpression of STIM1, MBP, SEPTIN9, and SEPTIN10 and the downregulation of CRACR2A, ORMDL3, SARAF, SEPTIN3, and SEPTIN6 in colon cancer cells." (PMID 36900391, 2023).
Glucose intolerance (1 paper, 2024). Glucose intolerance (GI) can be defined as dysglycemia that comprises both prediabetes and diabetes. "Because obese male ORMDL3TG mice had increased glucose intolerance, and insulin resistance correlates with adipocyte hypertrophy, chronic inflammation, and fibrosis, we asked whether overexpression of ORMDL3 influenced adipose remodelling." (PMID 38081412, 2024).
Hepatic steatosis (1 paper, 2024). Steatosis is a term used to denote lipid accumulation within hepatocytes. "Taken together, these results suggest that overexpression of ORMDL3 in obese mice bestows sexual dimorphism of hepatic steatosis, hypercholesterolemia, and exacerbated fibrosis, leading to the early development of NASH characteristics." (PMID 38081412, 2024).
hepatoma (1 paper, 2022). "In summary, it is shown that sorafenib can inhibit the growth of hepatoma in mice, and silencing the expression of ORMDL3 in liver cancer cells can increase the inhibitory effect of sorafenib on the growth of hepatoma in mice." (PMID 35972600, 2022). "First, Western Blot and RT-qPCR were used to detect the expression differences of ORMDL3 in human normal liver cells HL-7702 and human hepatoma cells HepG2 and SMMC-7721 in the presence or absence of sorafenib." (PMID 35972600, 2022).
Hereditary breast cancer (1 paper, 2019). Breast carcinoma that has developed in relatives of patients with history of breast carcinoma. "Among the highest-scoring genes detected using the proposed method, it is suspected that STARD3, PGAP3, ORMDL3, PSMD3 and HAPLN3 are the biomarkers of the HER2 + subtype, thus indicating that FOXC1 can identify basal-like subtypes in hereditary breast cancer cohorts." (PMID 31296201, 2019).
Hyperglycemia (1 paper, 2025). An increased concentration of glucose in the blood. "Collectively, our findings underscore a complex interplay between hyperglycemia-induced ER stress and autophagy in the diabetic intestine, positioning ORMDL3 as an orchestrator in the underlying pathogenesis and a potential therapeutic target for IBDs." (PMID 41182648, 2025).
hyperreactivity (1 paper, 2020). "Collectively, these findings imply that the genetic polymorphism of ORMDL3 may affect gene expression and subsequently sphingolipid synthesis and can play a pathogenic role in airway hyperreactivity of AERD." (PMID 33031402, 2020).
Insulin resistance (1 paper, 2024). Increased resistance towards insulin, that is, diminished effectiveness of insulin in reducing blood glucose levels. "Conversely, global deletion of Ormdl3 in mice fed an obesogenic diet increases weight gain and insulin resistance." (PMID 38081412, 2024).
liver cancer (1 paper, 2022). An epithelial or non-epithelial malignant neoplasm that arises from the liver. "Next, it was tested whether the increase in ROS levels caused by ORMDL3 silencing affected the apoptosis of liver cancer cells." (PMID 35972600, 2022). "Although the role of ORMDL3 in sorafenib resistance of liver cancer has been found, there are few studies on the role of the ORMDL3 gene in the occurrence and development of liver cancer and its molecular mechanism, which requires more research and discussion." (PMID 35972600, 2022). "The results of MTT showed that liver cancer cells with silenced ORMDL3 had a significantly reduced viability when compared with the control group, and the cell viability increased after combining with the oxidative stress inhibitor NAC." (PMID 35972600, 2022). "In combination with the autophagy activator, Rap, it was found that the ROS level in silenced ORMDL3 liver cancer cells was reduced, indicating that silencing ORMDL3 made the level of ROS in liver cancer cells to increase by inhibiting autophagy." (PMID 35972600, 2022). "Taken together, these data showed that silencing ORMDL3 can increase the inhibitory effect of sorafenib on the viability and proliferation of liver cancer cells, opening up new ideas for improving the sensitivity of sorafenib." (PMID 35972600, 2022). "The results showed that cell viability was significantly inhibited after sorafenib treatment, and the liver cancer cell viability was lower in ORMDL3-silenced group, which is consistent with the higher cell inhibition rate in ORMDL3-silenced group." (PMID 35972600, 2022). "The results showed that the expression of autophagy markers LC3 and Beclin1 in ORMDL3-silenced liver cancer cells was significantly decreased, while the expression of substrate recognition factor P62 was increased." (PMID 35972600, 2022). "In summary, these experimental results indicate that silencing ORMDL3 can increase ROS-mediated apoptosis of liver cancer cells by inhibiting autophagy." (PMID 35972600, 2022). "The results showed that under the action of sorafenib, the level of ROS in silenced ORMDL3 liver cancer cells was significantly higher than that of the control group, that is, silencing ORMDL3 can make the level of oxidative stress to increase in liver cancer cells." (PMID 35972600, 2022). "Although previous studies proved the relationship between ORMDL3 and ceramide in HepG2 hepatocarcinoma cells, its association with liver cancer is not completely clear." (PMID 35972600, 2022). "We used ATP kit to detect changes in mitochondrial energy of liver cancer cells, and the results showed that compared with the control group, the ATP level of cells was reduced under sorafenib treatment, and the ATP level of liver cancer cells with silenced ORMDL3 was lower." (PMID 35972600, 2022).
myasthenia gravis (1 paper, 2021). Myasthenia gravis (MG) is a rare, clinically heterogeneous, autoimmune disorder of the neuromuscular junction characterized by fatigable weakness of voluntary muscles. "We identified several genes that were specifically linked to early onset myasthenia gravis including TNIP1, ORMDL3, GSDMB, and TRAF3." (PMID 34279044, 2021).
non-alcoholic fatty liver disease (1 paper, 2024). "Next, it was of interest to examine the mechanism by which Ormdl3 overexpression induced sex differences in the development of diet-induced non-alcoholic fatty liver disease and steatohepatitis in mice." (PMID 38081412, 2024).
pulmonary disorders (1 paper, 2021). "Moreover, ORMDL3 is correlated with the degree of ER stress, whose deficiency protected mice from developing Alternaria-induced allergic airway inflammation, implying that ER stress inhibition may provide benefits for fungal allergen-induced pulmonary disorders." (PMID 34098934, 2021).
steatosis (1 paper, 2024). Increased lipid within the cytoplasm of cells. "Thus, a positive feedback loop may be created by hepatic sphingolipid accumulation to increase lipotoxicity-mediated sustained ER stress or maladaptive UPR that correlates with the sexual dimorphism of diet-induced development of steatosis and progression to NASH enhanced by Ormdl3 overexpression." (PMID 38081412, 2024).
triple-negative breast carcinoma (1 paper, 2021). An invasive breast carcinoma which is negative for expression of estrogen receptor (ER), progesterone receptor (PR), and human epidermal growth factor receptor 2 (HER2). "SOX21-AS1 also positively regulates the progression of triple-negative breast cancer via the miR-520a-5p/ORMDL3 axis." (PMID 34511042, 2021).
vitamin D deficiency (1 paper, 2024). A nutritional condition produced by a deficiency of VITAMIN D in the diet, insufficient production of vitamin D in the skin, inadequate absorption of vitamin D from the diet, or abnormal conversion of vitamin D to its bioactive metabolites. "Vitamin D deficiency differentially regulated the expression levels of several Chr17q12-21.1-encoded genes, with lower expression of Ikzf3, Ormdl3, and Gsdma (all p = 0.0286)." (PMID 38567749, 2024).
tumor (7 papers, 2016 to 2025). "The deficiency of ORMDL3 significantly suppressed LCC tumor growth compared to the control group." (PMID 40126553, 2025). "Decreased lymphocyte activity could facilitate tumor evasion of the immune system and explain the observed increased risk of cSCC among individuals with higher imputed expression levels of ORMDL3 in LCLs." (PMID 30323283, 2018). "However, we hypothesized that the association between down-regulation of ORMDL3 and worse survival prognosis as well as higher tumor grade is due to the possible tumor suppressor effect of ORMDL3." (PMID 30621577, 2019). "Collectively, these findings suggest that inhibition of tumor-intrinsic ORMDL3 amplifies anti-tumor immunity by increasing ISGs expression in TME and promoting cytotoxic CD8+ T cell activation." (PMID 40126553, 2025). "To assess the impact of ORMDL3 on anti-tumor activity, we conducted knockdown experiments targeting ORMDL3 in LLC and MC38 murine cancer cell lines, followed by subcutaneous inoculation into C57BL/6 mice." (PMID 40126553, 2025). "Animal experiments showed that inhibiting ORMDL3 enhances anti-tumor activity, demonstrated by an augmented proportion of activated CD8+ T cells and increased interferon production within the tumor microenvironment (TME)." (PMID 40126553, 2025). "Collectively, our findings reveal the pivotal roles of ORMDL3 in maintaining antiviral innate immune responses and anti-tumor immunity." (PMID 40126553, 2025). "The tumor volume growth rate of the control group and the ORMDL3-silenced group was the fastest, followed by the sorafenib group, and finally, the sorafenib group with ORMDL3 silenced." (PMID 35972600, 2022). "This tumor growth inhibition by targeting ORMDL3 was further validated in the MC38 cancer model." (PMID 40126553, 2025). "Moreover, investigations revealed that in the LLC tumor model, the knockdown of ORMDL3 led to a significant increase in the expression of ISGs, including Ccl5, Cxcl10, Tnf, and Il6, compared to the control group." (PMID 40126553, 2025). "Knockdown of ORMDL3 in LLC/MC38 cells enhances anti-tumor immunity." (PMID 40126553, 2025). "Moreover, the tumor weight was significantly lower in the group with sorafenib after silencing ORMDL3, as compared to the group with sorafenib alone." (PMID 35972600, 2022). "(a) ORMDL3 (b-e) breast cancer oncogenes (f-k) breast tumor suppressors." (PMID 30621577, 2019). "Collectively, our findings identify ORMDL3 as a negative regulator of type I IFN pathway and anti-tumor immunity." (PMID 40126553, 2025). "Consistent with CNV data, the ORMDL3 and ERBB2 expression levels were positively correlated for the tumor samples, but with a significant portion of outliers in the upper-left corner." (PMID 30621577, 2019). "So in this analysis, we conducted multivariable regression of the 3 modes of ORMDL3 expression only with ERBB2 for both survival and tumor grade data." (PMID 30621577, 2019). "In contrast, expressions of ORMDL1 and ORMDL3 non-significantly differed between tumor and normal brain tissues." (PMID 41049440, 2025). "(A–C) Representative images (A), tumor weight (B), and tumor growth (C) of LLC tumors on day 21 after inoculation with 1.5×106 LLC cells with or without Ormdl3 stable knockdown into C57BL/6 mice, (n=6)." (PMID 40126553, 2025). "(G–I) Representative images (G), tumor weight (H), and tumor growth (I) on day 27 after tumor inoculation with 5×105 MC38 cells with or without Ormdl3 stable knockdown into C57BL/6 mice, (n=6)." (PMID 40126553, 2025). "Additionally, subcutaneous syngeneic tumor models in C57BL/6 mice revealed that inhibition of ORMDL3 enhances anti-tumor efficacy by augmenting the proportion of cytotoxic CD8 positive T cells and IFN production in the tumor microenvironment (TME)." (PMID 40126553, 2025).
tumor (continued). "The proposed working model is that ORMDL3 forms a complex with MAVS and promotes the degradation of RIG-I, thereby attenuating the transcription of type I IFN and cytotoxic CD8+ T cell-mediated tumor killing." (PMID 40126553, 2025). "Interestingly, the expression of ORMDL3 in ordinary-luminal is lower than the average level of control samples, while it is higher for the HER2-amplified luminal tumours." (PMID 27341628, 2016). "Interestingly, ORMDL3 expression showed a negative correlation with CD8+ T cell activation markers such as PRF1, GZMA, and GZMB, as well as with ISGs such as CCL5 and CXCL10, validating our finding that ORMDL3 serves as a negative regulator of the IFN signaling pathway and anti-tumor immunity." (PMID 40126553, 2025). "No expression difference was noted for ORMDL3 between tumor and adjacent tissues." (PMID 38596689, 2024). "In conclusion, subcutaneous tumor transplantation experiment showed that sorafenib could inhibit the growth of mouse hepatocellular tumors, while silencing HCC cell ORMDL3 could increase the inhibitory effect of sorafenib on the growth of mouse hepatocellular tumors." (PMID 35972600, 2022). "Down-stream analysis suggests the oncogenic effect of ORMDL3 may be an artefact by its nearby oncogene ERBB2 amplification, while its tumor suppressor role cannot be ruled out." (PMID 30621577, 2019).
cancer (6 papers, 2019 to 2026). A tumor composed of atypical neoplastic, often pleomorphic cells that invade other tissues. "ORMDL3 is involved in sphingolipid metabolism, which has been linked to various cellular processes important in cancer, including cell growth, apoptosis, and response to therapy." (PMID 38596689, 2024). "Collectively, our results unveil the critical role of ORMDL3 in maintaining the homeostasis of antiviral innate immune responses and suggest ORMDL3 as a candidate target for cancer immunotherapy." (PMID 40126553, 2025). "This upregulation of ISGs upon ORMDL3 knockdown was consistent in the MC38 cancer model, where Ifnb1, Ccl5, and Cxcl10 mRNA levels were significantly elevated." (PMID 40126553, 2025). "We further analyzed ORMDL3 expression in the TCGA-pan-cancers cohort." (PMID 40126553, 2025). "However, the relationship between ORMDL3 and cancer needs more exploration." (PMID 35972600, 2022). "There are plenty of regulatory proteins, including CRACR2A, SEPTIN4, STIMATE, GOLLI, SARAF, ORMDL3 and so on, that contribute to alter SOCE activity in cancer, immune diseases and inflammation disorders." (PMID 36128650, 2022).
infection (3 papers, 2021 to 2025). The state of being infected such as from the introduction of a foreign agent such as serum, vaccine, antigenic substance or organism. "In order to investigate the potential role of ORMDL3 in the antiviral response, HEK293T cells overexpressing ORMDL3 were stimulated with poly(I:C) or vesicular stomatitis virus (VSV) infection." (PMID 40126553, 2025). "In this report, we found ORMDL3 knockdown epithelial cells release less IL-6 after HRV16 infection, consistently confirm the results from poly I:C stimulations in ORMDL3 knockdown cells." (PMID 34001091, 2021). "Nonetheless, our study raises the possibility that downregulation of ORMDL3 during infection with RV, and potentially other viruses, plays a role in the strong association of this locus with early life wheezing." (PMID 34629083, 2021). "To solve these problems, we will use air–liquid interface cultured human bronchial epithelium, which is known to be well infected with HRV16, The viral attachment, replication and inflammatory response of HRV16 infection for ORMDL3 knockdown epithelial cells need to be future in-depth investigation." (PMID 34001091, 2021).
ORMDL3 also shares sentences with these, for which no sentence is quoted: ulcerative colitis (8 papers); rheumatoid arthritis (5); Childhood onset (3); allergic rhinitis (2); Onset (2); primary biliary cholangitis (2); Alzheimer disease (1); amyotrophic lateral sclerosis (1); anaphylaxis (1); atopic dermatitis (1); basophilic leukaemia (1); cholangitis (1); chronic asthma (1); chronic rhinosinusitis (1); dermatitis (1); dyslipidemia (1); eczema (1); esophageal adenocarcinoma (1); Hypercholesterolemia (1); hypothyroidism (1); immune diseases (1); lung adenocarcinoma (1); lung squamous cell carcinoma (1); metabolic disease (1); multiple sclerosis (1); non-alcoholic steatohepatitis (1); pancreas cancer (1); Parkinson disease (1); respiratory disease (1); rhinitis (1).
A further 4 diseases each share a sentence with ORMDL3 in 1 paper.